DYNLT2B (dynein light chain Tctex-type 2B)
Description:
Acts as one of several non-catalytic accessory components of the cytoplasmic dynein 2 complex (dynein-2 complex), a motor protein complex that drives the movement of cargos along microtubules within cilia and flagella in concert with the intraflagellar transport (IFT) system. Required for proper retrograde ciliary transport.
Synonyms: TCTEX1D2; MGC33212; SRTD17
Tractability: Small molecule: a structure with a bound ligand is known. PROTAC: ubiquitination databases record sites on it.
Gene: Protein-coding gene on chromosome 3 (196,291,219 to 196,318,310, reverse strand). Ensembl gene ENSG00000213123.
Subcellular location: Dynein axonemal particle
Subcellular location (Human Protein Atlas): Microtubules; Primary cilium; Basal body; Cytosol; Mitotic spindle
Pathways (Reactome):
Organelle biogenesis and maintenance: Intraflagellar transport
Gene Ontology:
Molecular function: dynein intermediate chain binding; protein binding
Biological process: cilium assembly; intraciliary retrograde transport; regulation of cilium assembly; regulation of intraciliary retrograde transport; microtubule-based movement
Cellular component: axoneme; centrosome; ciliary base; cytoplasmic dynein complex; interphase microtubule organizing center; spindle pole; cilium; cytoplasm; dynein complex; male germ cell nucleus; dynein axonemal particle
Genetic constraint (gnomAD): Loss-of-function variants: 13 observed, 16.72 expected, observed/expected ratio (o/e) 0.78, 90% interval 0.5 to 1.24. The upper end of that interval is the gene's LOEUF score, 1.24, which puts it in group 5 of 6, group 1 being the genes least tolerant of losing a copy. Missense variants: 129 observed, 155.68 expected, observed/expected ratio (o/e) 0.83, 90% interval 0.72 to 0.96. Synonymous variants: 70 observed, 52.74 expected, observed/expected ratio (o/e) 1.33, 90% interval 1.09 to 1.62.
Gene-disease validity (ClinGen):
ClinGen rates the evidence that DYNLT2B causes each of these diseases.
short-rib thoracic dysplasia 17 with or without polydactyly (autosomal recessive): Limited.
Homologues: Orthologues: rabbit DYNLT2B (93% identical), dog DYNLT2B (91% identical), pig DYNLT2B (89% identical), chimpanzee DYNLT2B (87% identical), guinea pig DYNLT2B (87% identical), mouse Dynlt2b (83% identical), rat Dynlt2b (82% identical), macaque DYNLT2B (75% identical), rat Dynlt2b-ps1 (75% identical), tropical clawed frog dynlt2b (63% identical), zebrafish dynlt2b (48% identical), Caenorhabditis elegans dylt-2 (30% identical), and 1 more. Paralogues in human: DYNLT5 (32% identical), DYNLT4 (30% identical), DYNLT2 (25% identical), DYNLT1 (20% identical), DYNLT3 (18% identical).
Diseases named in the same sentence as DYNLT2B in open-access papers:
DYNLT2B is named in the same sentence as 4 diseases in open-access papers, as found by Europe PMC text mining. Sharing a sentence is not in itself a finding about the gene and the disease.
DYNLT2B shares sentences with these, for which no sentence is quoted: ciliopathy (6 papers); Jeune syndrome (2); Failure to thrive (1); PHACE syndrome (1).